RNVU1-22 (RNA, variant U1 small nuclear 22)
Synonyms: RNU1-120P
Gene: Small nuclear RNA gene on chromosome 1 (148,263,476 to 148,263,632, forward strand). Ensembl gene ENSG00000199879.
Gene Ontology:
Molecular function: pre-mRNA 5'-splice site binding
Biological process: mRNA 5'-splice site recognition
Cellular component: U1 snRNP
Homologues: Orthologues: chimpanzee U1 (80% identical), macaque U1 (72% identical), rabbit U1 (60% identical), zebrafish U1 (48% identical). Paralogues in human: RNU1-1 (76% identical), RNU1-2 (76% identical), RNU1-27P (76% identical), RNU1-28P (76% identical), RNU1-3 (76% identical), RNU1-4 (76% identical), RNVU1-18 (76% identical), RNVU1-29 (76% identical), RNVU1-2A (76% identical), U1 (76% identical), RNVU1-17 (75% identical), RNVU1-19 (75% identical), and 133 more.